FGF21 (fibroblast growth factor 21)
Diseases named in the same sentence as FGF21 in open-access papers (continued):
Sharing a sentence is not in itself a finding about the gene and the disease.
Hypoglycemia (23 papers, 2013 to 2025). A decreased concentration of glucose in the blood. "In general, males and females equally responded to the corresponding metabolic situation: fasting caused decrease of body and liver weights, loss of fat stores, hypoglycemia, decrease of leptin and increase of FGF21 and adiponectin blood levels." (PMID 31783664, 2019). "The reason underlying the increased risk for alcohol-induced hypoglycemia post-metabolic surgery is unclear, but we hypothesize it may be related, at least in part, to alcohol’s greater inducement of fibroblast growth factor 21 (FGF21) after surgery." (PMID 40474966, 2025). "They observed increased Fgf21 and lower Pck1 transcript levels, which counteracts hypoglycemia and energy imbalance." (PMID 34129049, 2021). "Like FGF21 knockout mice, PPARα knockout mice exhibited similar phenotypes such as hypoglycemia and impaired hepatic gluconeogenesis." (PMID 34572066, 2021). "In this study, fasting FGF21 knock-out mice displayed severe hypoglycemia and impaired hepatic gluconeogenesis." (PMID 34572066, 2021). "FGF21 levels can explain the observed metabolic changes, such as basal hypoglycemia, liver growth hormone (GH) resistance, and conditional knockout mice’s reduced animal size." (PMID 33374852, 2020). "The increase of FGF21 can explain the observed metabolic changes, such as basal hypoglycemia, liver GH resistance, and the reduced animal size of conditional knockout mice." (PMID 31189900, 2019). "A previous clinical study indicated that the lipid-lowering effect of FGF21 is more significant than that of hypoglycemia in humans 126, enlightening us to explore the potential of applying FGF21 with clinical antidiabetic drugs instead of applying FGF21 alone." (PMID 36594101, 2023). "Administering GLP-1 and FGF21 in combination was not expected to pose a risk of hypoglycemia, as each respective agonist is believed to contain built-in safety mechanisms preventing dangerous dips in blood glucose." (PMID 32923621, 2020). "We have previously shown that mTORC1 activation induces the release of fibroblast growth factor 21 (FGF21) from the skeletal muscle, which in turn is responsible for several of the metabolic changes, such as hypoglycemia, increased fatty acid oxidation, and reduced body weight." (PMID 27004103, 2016). "This difference is likely a reflection of the inability of FGF21 to induce hypoglycemia in animals." (PMID 23536797, 2013). "Interestingly, FGF21 injection does not cause hypoglycemia in rodents and primates, and studies have shown that FGF21 can act directly on the pancreas to regulate its function." (PMID 29949887, 2018). "The initial increase of Fgf21 in 70 days DKO muscles and blood can explain the observed metabolic changes such as basal hypoglycemia and reduced epididymal pads." (PMID 31208084, 2019). "As previous reported, fasted FGF21−/− mice exhibit impaired activation of the hypothalamic–pituitary–adrenal (HPA) axis and blunted release of corticosterone, which could lead to hypoglycemia and defective hepatic gluconeogenesis." (PMID 40021824, 2025). "First, FGF-21 can mitigate metabolic disorders without inducing hypoglycemia or mitogenesis, which shows the future significance of FGF-21-based therapies for metabolic diseases." (PMID 36238554, 2022). "Most importantly, they found that FGF-21 does not induce mitogenesis and hypoglycemia, indicating that FGF-21 is an ideal drug for metabolic diseases." (PMID 36238554, 2022). "Studies have demonstrated that FGF21 can also significantly reduce fasting blood glucose level and improve glucose clearance without hypoglycemia." (PMID 35884970, 2022). "Consistent with our present findings, FGF21 did not induce hypoglycemia, even in fasted FGF21-transgenic mice." (PMID 28225059, 2017). "However, there has been no previous report of hypoglycemia-induced elevations of FGF-21 to our knowledge." (PMID 37400734, 2023).
Hypoglycemia (continued). "Notably, FGF-21 can significantly mitigate metabolic disorders without inducing hypoglycemia or mitogenesis, further implying its significant potential in clinical applications." (PMID 36238554, 2022). "Moreover, the muscle defects are transmitted systemically through muscle release of fibroblast growth factor 21 (FGF21), together with inflammatory cytokines such as interleukin 6 (IL6) inducing hypoglycemia, lipolysis, liver steatosis, inflammation, a pro-senescent phenotype, and premature death." (PMID 33374852, 2020). "However, unlike insulin, studies in rodents and primates showed that FGF21 normalizes blood glucose levels without inducing hypoglycemia even at a very high dose (i.e., there is a ceiling effect by which FGF21 decreases blood glucose no further)." (PMID 30802174, 2019). "Furthermore, FGF-21 provided sustainable glucose control without incidence of hypoglycemia and a substantial improvement in lipid abnormalities and several cardiovascular risk factors." (PMID 24260557, 2013).
Impaired glucose tolerance (23 papers, 2011 to 2025). An abnormal resistance to glucose, i.e., a reduction in the ability to maintain glucose levels in the blood stream within normal limits following oral or intravenous administration of glucose. "In contrast, plasma FGF21 levels after bariatric surgery decreased significantly in patients with impaired glucose tolerance or T2D (p < 0.05)." (PMID 40377893, 2025). "It has been documented that patients with impaired glucose tolerance and T2D have increased levels of circulating FGF21 as a compensatory mechanism." (PMID 40040308, 2025). "There have been reports that T2D patients and impaired glucose tolerance had elevated levels of circulating FGF21 as a compensatory strategy." (PMID 40040308, 2025). "The elevated circulating FGF21 levels have been seen in the context of impaired glucose tolerance and increased accumulation of lipid in the liver." (PMID 28466020, 2017). "FGF21 KO animals were slightly heavier and had impaired glucose tolerance and higher levels of circulating NEFAs, even in the fasted state." (PMID 26872145, 2016). "They found FGF21 levels in patients with T2DM were significantly higher than those with impaired glucose tolerance (IGT) or normal glucose tolerance (NGT)." (PMID 26540514, 2015). "Increases in serum FGF21 have been reported in obese and/or impaired glucose tolerance patients; however, it is unclear whether glucose can activate human FGF21 gene expression." (PMID 21829679, 2011).
fibrosis (22 papers, 2013 to 2026). the formation of excess fibrous connective tissue in an organ or tissue in a reparative or reactive process. "FGF21 analogue treatment significantly increased the likelihood of achieving ≥ 1-stage fibrosis improvement (RR: 2.25, CI: 1.25-4.03) compared with placebo." (PMID 42255485, 2026). "Three FGF21 analogs are currently in phase IIb/3 clinical development for MASH-related fibrosis: efruxifermin, pegozafermin, and efimosfermin." (PMID 40590228, 2025). "In vitro experiments showed that FGF21 significantly decreased myofibroblast markers α-SMA and ACTA2 mRNA levels, suggesting that FGF21 was related to attenuating cardiac fibrosis." (PMID 37416922, 2023). "This review summarizes the biological effects of FGF21 and discusses what is currently known about this factor and fibrosis disease, highlighting emerging insights that warrant further research." (PMID 35677107, 2022). "The molecular downstream mechanisms by which an FGF21 analogue mitigates hepatic fibrosis, therefore, remains to be clarified." (PMID 29444136, 2018). "We investigated the association of serum FGF21, FGF19 and liver Klotho coreceptor with non-alcoholic steatohepatitis (NASH) and fibrosis in children with NAFLD." (PMID 23840612, 2013). "Moreover, we evaluated the regulation of > 1000 genes coding for ECM remodelling, and although the expression of COLs, laminins and ADAMs/ADAMTS increased with fibrosis grades, we obtained clear evidence for an antifibrotic function of FGF21." (PMID 39962359, 2025). "FGF21 ameliorates hepatic fibrosis by multiple mechanisms, such as inhibition of TGF-β." (PMID 37874393, 2023). "Moreover, offspring of HFD dams had altered methylation patterns in DMRs of genes that play important roles in hepatic fibrosis and lipid accumulation, including Ppargc1β, Fgf21, Ephb2 and VWF." (PMID 28414763, 2017). "A previous study reported that FGF21 could ameliorate hepatic fibrosis through multiple mechanisms." (PMID 39040469, 2024). "Their findings suggested that FGF21 analogs appear promising in the treatment of MASH and MASH-related fibrosis, with generally good safety and tolerability profiles." (PMID 40520164, 2025). "FGF21 levels were associated with biomarkers of NASH and histopathologic scoring (F3-F4 fibrosis) in female patients but we did not observe a significant correlation based on the whole cohort." (PMID 35743140, 2022).
pancreatitis (22 papers, 2013 to 2025). Inflammation of the pancreas. "Further study revealed that the transcription factor MIST1 was an upstream regulator for FGF21, and MIST1 deletion resulted in significantly reduced pancreatic FGF21 levels through epigenetic silencing, thereby increasing susceptibility to pancreatitis." (PMID 36618930, 2022). "FGF21 also protects the exocrine pancreas from pancreatitis induced by cerulein, associated with accumulation of reactive oxygen species, immune infiltration, and exocrine dysfunction." (PMID 33381084, 2020). "FGF21 KO mice are more susceptible to cerulein-induced pancreatitis (CIP), while FGF21 transgenic mice are resistant to acute pancreatitis." (PMID 30927227, 2019). "Further studies identified the transcription factor MIST1 as an upstream regulator for FGF21 and deletion of Mist1 gene leads to a marked reduction in pancreatic FGF21 levels by epigenetic silencing which results in increased susceptibility to pancreatitis." (PMID 26872145, 2016). "FGF21 deficiency increases the susceptibility of mice to cerulein-induced pancreatitis and toxicity of sepsis, as well as acetaminophen-induced liver injury, suggesting a potentially protective effect of FGF21 against acute organ injury." (PMID 25991671, 2015). "FGF21 also functions as a secretagogue to promote pancreatic exocrine function and maintain acinar cell proteostasis, which if uncontrolled could cause pancreatitis." (PMID 33668583, 2021). "Similarly, FGF21 deficient mice have exacerbated experimental pancreatitis, while FGF21-KO mice consuming a conventional obesogenic high fat, high sucrose diet develop exaggerated peri-portal pancreatic inflammation." (PMID 29107287, 2017). "Relative changes in FGF21 may be associated with pancreatitis severity, and subjects with alcohol-induced pancreatitis tended to have higher maximum FGF21 levels." (PMID 27832059, 2016). "Interestingly, FGF21 has also proven to be beneficial in conditions associated with inflammation such as pancreatitis or sepsis in animal models, suggesting a role of FGF21 in modulating inflammation." (PMID 23999826, 2013). "In pancreatitis, the expression of Fgf21 in pancreatic cells is significantly increased, and the severity of injury is inversely related to the expression of Fgf21." (PMID 40218937, 2025). "In the pancreas, FGF21 is abundantly expressed under normal conditions but is markedly downregulated during pancreatitis and pancreatic ductal adenocarcinoma (PDAC)." (PMID 41426308, 2025). "The critical role of FGF-21 in safeguarding the function of the exocrine pancreasand suggesting its potential therapeutic target in preventing and treating pancreatitis." (PMID 39139157, 2024). "ATF3 and FGF-21 expression patterns in the pancreas of human patients with pancreatitis were found to be consistent with those seen in mice, supporting previous research." (PMID 39139157, 2024). "The restoration of FGF-21 expression and relief from pancreatitis was also brought about by suppressing the ISR using an inhibitor of PKR-like endoplasmic reticulum kinase (PERK)." (PMID 39139157, 2024). "Fgf21 expression disappears in the dedifferentiated acinar tissue of induced-pancreatitis, and administration of Fgf21 restores pancreatic levels and acinar function dramatically." (PMID 37796967, 2023). "Studies suggest a regulatory role of FGF21 in the tissue injury induced by experimental pancreatitis, in which FGF21 null mice produced more severe damage than wild-type mice, whereas mice with overexpressing FGF21 showed an attenuated phenotype." (PMID 36618930, 2022). "Deficiency of FGF21 under pancreatitis induced by caerulein, thapsigargin, or mechanical stress worsened pancreatitis and precipitated overt organ damage, while overexpression of FGF21 reversed these effects." (PMID 33668583, 2021). "Despite the fact that FGF21 is highly expressed in the pancreas, little is known about its role in pancreatitis." (PMID 32233059, 2020).
pancreatitis (continued). "In the context of reports on FGF21 in experimental pancreatitis, FGF21 has been shown to have a direct protective effect under conditions of stress." (PMID 26872145, 2016). "Our findings are consistent with reports showing that pancreatic FGF21 expression increases in mice with cerulein-induced pancreatitis." (PMID 27832059, 2016). "We have shown that serum FGF21 levels are increased in human pancreatitis, which is consistent with prior data in mice and humans." (PMID 27832059, 2016). "We found that, in patients with pancreatitis, serum FGF21 rises significantly and peaks four to six days after the maximum lipase level, before slowly declining." (PMID 27832059, 2016). "We controlled for the known variation of FGF21 with BMI by selecting control subjects within the same range of BMI as the pancreatitis subjects (28.6 (range 21–35.5) vs. 29.3 (range 19.1–46) for acute pancreatitis subjects, P = 0.73)." (PMID 27832059, 2016). "Another study has shown that in mice with cerulein-induced pancreatitis, the expression of FGF21 increased rapidly and dramatically." (PMID 23999826, 2013). "The expression of FGF21 is down regulated in a pancreatitis model." (PMID 36505827, 2022). "Supplementation with FGF21 can directly act on the exocrine function of the pancreas to reverse pancreatitis, which is manifested as a reduction in plasma amylase levels, alleviation of pancreatitis edema, and inflammatory infiltration and necrosis." (PMID 36505827, 2022). "In addition, FGF21 appears to be required to protect mice against experimental pancreatitis, as FGF21 KO mice exhibit more damage, while FGF21Tg/Tg mice are protected from damage, following cerulein-induced pancreatitis." (PMID 35046901, 2021). "It was found that the expression of FGF21 increased during the development of AP, and FGF21 may play an important role in pancreatitis." (PMID 32233059, 2020). "Thus far, fructose challenge, protein restriction, muscle myopathies, fatty liver and pancreatitis are consistent in elevating FGF21 levels in both species." (PMID 29107287, 2017). "Thus far, limited studies suggest that FGF21 has a role in modulating inflammation and damage induced by experimental pancreatitis." (PMID 26872145, 2016). "FGF21 can also reduce the severity of cerulein-induced pancreatitis in mice, further indicating that FGF21 could modulate inflammation." (PMID 23999826, 2013). "In this regard, Fgf21 may provide an effective treatment for pancreatitis." (PMID 37796967, 2023). "A number of studies have revealed that FGF21 is expressed also at high levels at normal conditions in the pancreas, in particular the pancreatic acinar cells, which can be further induced in response to pancreatic perturbations, such as the fatty pancreas, pancreatitis, and pancreatic injury." (PMID 33668583, 2021). "However, with the persistence of pancreatitis, subsequent ATF3 induction effectively inhibits FGF21 transcription and plays an important role in contributing to CP." (PMID 36505827, 2022). "The onset of pancreatitis is initially induced by ATF4, with a concomitant increase in FGF21, which may indicate a preliminary attempt to overcome pancreatic tissue damage." (PMID 36505827, 2022). "In our study, Fgf21 was downregulated in CP and recovered partially in CPR and was involved in 2 of the top 20 gene sets, supporting a protective role of Fgf21 in pancreatitis." (PMID 34104113, 2021). "Maximum but not baseline FGF21 levels were higher in subjects with alcohol-induced pancreatitis compared to those with pancreatitis of a different etiology (3077 ± 897 vs. 1210 ± 310 pg/mL, P = 0.02)." (PMID 27832059, 2016). "Maximum FGF21 levels did not correlate with pancreatitis severity; however, the fold increase was greater in severe compared to mild but not moderately severe pancreatitis (4.4 ± 1.0 for mild, 5.5 ± 1.6 for moderately severe, 18.2 ± 11.8 for severe, P = 0.01 mild vs. severe)." (PMID 27832059, 2016).